TNF (tumor necrosis factor)
Diseases named in the same sentence as TNF in open-access papers (continued):
Sharing a sentence is not in itself a finding about the gene and the disease.
tumor (continued). "This modality additionally amplifies proinflammatory cytokine secretion (notably IL-6 and TNF-α) that cooperates with ICIs to intensify T cell-dependent anti-tumor activity." (PMID 40445365, 2025). "Cytokines, including TNF-α, IL-10, IL-8, and IL-6, are also released by the tumor stroma, and are identified as chemotactic, immunosuppressive, and pro-survival signals, further supporting EMT induction." (PMID 39941895, 2025). "ELISA revealed that 015s markedly reduced active TGF-β1 in serum and tumour tissue while significantly increasing intratumoural cytokines, such as TNFα and IFN-γ." (PMID 40806691, 2025). "These cytokines represent complementary aspects of the tumor microenvironment: pro-inflammatory and tumor-promoting signaling (IL-6, IL-1β, TNF-α), anti-inflammatory modulation (IL-10), and Th17-driven immune activity (IL-17)." (PMID 41267807, 2025). "M1-type macrophages kill tumor cells by releasing reactive oxygen species (ROS), nitric oxide (NO), and pro-inflammatory cytokines, TNF-α, IL-6, IFN-γ, over days and through antibody-dependent cell-mediated cytotoxicity (ADCC) within hours." (PMID 40260236, 2025). "It is thought that TNF-α is another crucial proinflammatory cytokine that often acts as a tumor promoter when chronically elevated." (PMID 41614883, 2025). "MyD88 was required for induction of IL-6 and TNF-α, activation of MDSCs, and tumor metastasis mediated by tumor-derived exosomes." (PMID 40443670, 2025). "Tumor-derived factors such as interleukin-6 (IL-6), tumor necrosis factor-alpha (TNF-α), and granulocyte colony-stimulating factor (G-CSF) stimulate neutrophil proliferation and activation." (PMID 41180708, 2025). "The results showed that APS not only suppressed tumour growth, but also significantly increased the thymus and spleen indices and enhanced the production of serum cytokines IL-2, IL-6, and TNF-α." (PMID 40649307, 2025). "In vitro experiments using human mammary stromal cells revealed that TNF-α treatment promotes an inflammatory microenvironment, facilitating tumor progression." (PMID 40430573, 2025). "These inflammatory cells release interleukin-6 (IL-6), tumor necrosis factor-α (TNF-α) in tumor tissues, which activate multiple signaling pathways to promote tumor cell proliferation, survival, invasion and metastasis." (PMID 41256327, 2025). "And this polarization increased the levels of TNF-α while inhibiting the expression of transforming growth factor-β, thereby remodeling the tumor microenvironment." (PMID 41467185, 2025). "On the one hand, β-TrCP activates NF-κB signaling by degrading IκB (NF-κB inhibitors), promotes the release of pro-inflammatory factors (such as TNF-α, IL-6), and enhances the survival and metastasis of tumor cells." (PMID 40534867, 2025). "In conjunction with radiotherapy and chemotherapy, TNF-α improves tumor cell sensitivity to apoptosis produced by therapy, boosting overall therapeutic response." (PMID 40309351, 2025). "The infiltration of CTLs within the tumor, as well as the expression of GrzB and TNF-α in these CTLs, was significantly enhanced when CBG was combined with αPD-L1 therapy." (PMID 39990210, 2025). "CAR T cells derived from cocultures with imMac exhibited impaired production of effector cytokines IFN-g and tumor necrosis factor-alpha (TNF-a) and demonstrated decreased ability to lyse target tumor cells." (PMID 40235478, 2025). "Tumor cells and surrounding immune cells release cytokines such as tumor necrosis factor-alpha (TNF-α), interleukin-6 (IL-6), and interleukin-1β (IL-1β)." (PMID 41180630, 2025). "M1 macrophages predominantly secrete pro-inflammatory cytokines (IL-6, IL-12, TNF-α) that drive anti-tumor immunity." (PMID 40426851, 2025). "Beyond direct killing, CTLs secrete cytokines like interferon-γ (IFNγ) and tumor necrosis factor-α (TNFα), which further stimulate anti-tumor immunity." (PMID 40475782, 2025).
tumor (continued). "Inflammatory mediators, such as IL-6, TGF-β, and TNF-α contribute to cancer-related inflammation via the interaction between inflammatory cells and tumor cells." (PMID 41614883, 2025). "TNF-α upregulation is involved in the angiogenesis process in the tumor microenvironment, affecting the tumor’s nutrient supply and waste removal, creating favorable conditions for tumor growth, and promoting tumor cell migration and invasion." (PMID 40429988, 2025). "Collectively, TNF-α-modified endothelial cells create a tumor-supportive microenvironment via EndMT and EMT, both of which are critical for tumor invasion and metastasis, with NF-κB integrating inflammatory and oncogenic signals." (PMID 40558596, 2025). "Like IL-6, TNF-α contributes to tumorigenesis by promoting cell proliferation, angiogenesis, metastasis, and even participating in the early stages of tumor initiation." (PMID 41267807, 2025). "Mechanistically, we discovered that macrophages inhibit the pyrimidine salvage pathway in tumor cells by upregulating Upp1-mediated uridine degradation through cytokines TNF-α and IL-1." (PMID 41243973, 2025). "The efficacy of low doses of IFN-γ and TNF-α have been reported in different tumor contexts and validated in some clinical settings." (PMID 41102150, 2025). "When primed by inflammatory cytokines (IFN-γ, TNF-α, IL-1β), MSCs secrete IL-15, IL-12, and type I interferons, which are critical for maintaining NK cell cytotoxicity and survival in hostile tumor settings." (PMID 40643499, 2025). "M1-type TAMs secrete factors that exert anti-tumor effects: IL-12, TNF-α, and IL-1β activate cytotoxic T cells and NK cells, and CXCL9 recruits Th1 cells and cytotoxic T cells to the TME, enhancing anti-tumor immunity." (PMID 40375990, 2025). "Whereas, in another experiment, the mangiferin encapsulated AuNPs on PC-3 cells reduced the IL-6 and IL-10 (pro-tumor) and increased the TNF-α and IL-12 expression in the treated groups." (PMID 40712409, 2025). "Here, we identified CRC‐specific RNA modifications in EVs that promote tumour growth by enhancing tumour necrosis factor (TNF)‐α and interleukin (IL)‐6 secretion by macrophages." (PMID 40326665, 2025). "Tumor-suppressing N1 neutrophils release pro-inflammatory factors like tumor necrosis factor-α (TNF-α), IL-12, CXCL9, and CXCL10." (PMID 40362673, 2025). "Specifically, TNF-NF-κB signaling can activate tumor-associated macrophages (TAMs), induce M2 polarization, and foster an immunosuppressive TME that facilitates tumor proliferation, angiogenesis, and distant metastasis." (PMID 40999361, 2025). "Of note, MCs represent the only cell type able to store preformed TNF-α in their granules and, upon exocytosis, can exhibit antitumor activity through direct tumor cell cytotoxicity mediated by TNF-α and reactive oxygen species." (PMID 40372523, 2025). "Reduced tumor cell susceptibility to CD8+ T-cells was associated with increased IL-6 expression and reduced TNF-α and IFN-γ levels." (PMID 39883638, 2025). "The study found that OP bone fragments increased the release of pro-inflammatory cytokines, such as TNF-α, IL-6, IL-1β, and IL-8, which regulate immune cell activity in the tumor microenvironment." (PMID 40584290, 2025). "These molecules, along with HMBPP produced by pathogens like Gram-negative bacteria and malaria parasites, activate γδ T cells to release inflammatory cytokines IFN-γ and TNF -α, which kill tumor cells." (PMID 40370457, 2025). "CAFs also secrete various molecules, such as platelet-derived growth factor (PDGF), human growth factor (HGF), vascular endothelial growth factor (VEGF), TNFα, and stromal cell-derived factor, to enhance tumor progression and inflammation." (PMID 40165901, 2025). "Secretion of IL-2, IFN-γ, and TNF-α by these cells directly suppresses tumor growth while simultaneously enhancing the cytotoxic activities of other immune components." (PMID 41320679, 2025).
tumor (continued). "Our findings are consistent with these results, as G31P inhibited CXCL1, CXCL2 and TNF-α in tumor and bleomycin-induced lung tissues, alongside decreased MPO activity and F4/80+ macrophage infiltration." (PMID 41425704, 2025). "They prevent tumor growth through the secretion of pro-inflammatory cytokines known to inhibit tumor progression, including tumor necrosis factor-alpha (TNF-α), interleukin-1β (IL-1β), IL-6, IL-8, IL-12, and IL-23." (PMID 39857798, 2025). "Inflammatory cells, such as macrophages, neutrophils, and lymphocytes, infiltrate the tumor microenvironment and secrete pro-inflammatory cytokines, including interleukin-6 (IL-6) and tumor necrosis factor-alpha (TNF-α)." (PMID 40428567, 2025). "We next determined the serum levels of IFN-γ and TNF-α, given their potential involvement in the tumor control effect mechanism of triple therapy." (PMID 40109871, 2025). "In fact, SCFA enhance the CD8+ cytotoxic activity and CAR T-cells by reducing histone deacetylases and increasing IL-12 responses, leading to the production of interferon-γ (IFNγ) and tumor necrosis factor (TNF), thus concurring in anti-tumor immunity." (PMID 40944286, 2025). "The antibodies against IFN-γ were found to induce a greater inhibition of hA549 tumor differentiation compared to antibodies against TNF-α." (PMID 39851518, 2025). "To explore the therapeutic potential of targeting TNF-α, we treated a highly aggressive KPC tumor model with an anti-TNF-α monoclonal antibody plus GEM." (PMID 39762215, 2025). "Tumoral organoids have been shown to activate MCs via the IL-33/ST2 axis leading to increased release of TNF-α which in turn was responsible for the observed effects on tumoral organoids." (PMID 40372523, 2025). "Assessment indicators included tumour weight and inhibition rate, spleen and thymus indices, serum cytokine levels (IL-2, IL-12, TNF-α, IL-10), as well as the phagocytic rate and phagocytic index of peritoneal macrophages." (PMID 40649307, 2025). "TNF dual role of TNF signaling in tumor growth, necroptosis, and inflammatory remodeling presents therapeutic challenges." (PMID 41584509, 2025). "This inhibition is accompanied by the modulation of pro- and anti-apoptotic proteins BAX and BCL-2, a reduction in MYCN mRNA expression, and a decrease in TNF-α secretion, suggesting a direct impact on tumor growth and cell survival." (PMID 40942095, 2025). "Recent studies have begun exploring the relationship between TNF-α and these established tumor markers, with preliminary evidence suggesting that elevated TNF-α levels correlate with worse overall and 5-year survival rates." (PMID 40299527, 2025). "The treatment of mice with anti–PD-L1 combined with bacteria provided analogous control of tumor growth as the combination of the antibody with apyrase as well as a similar increase in TNF-α+Granzyme B+ and CXCR5+ CD8 TILs." (PMID 41042869, 2025). "Cytokines and growth factors, such as interleukin-6 (IL-6), interleukin-8 (IL-8), and tumor necrosis factor-alpha (TNF-α), are often elevated in the saliva of patients with OSCC, indicating tumor-associated inflammation." (PMID 41502517, 2025). "Engagement of the CD40 pathway significantly increases the production of pro-inflammatory cytokines like TNF-α, IL-12, and IL-6, which are crucial in driving the anti-tumor immune response and promoting inflammation." (PMID 40055311, 2025). "This suppressed PI3Kγ signaling, reducing the expression of M2 markers (CD206 and IL-10) and increasing the expression of M1 markers (CD86 and TNF-α), which inhibited tumor growth by reprogramming TAMs in 4T1 and MC38 mouse models." (PMID 40850976, 2025). "In the breast cancer tumor-bearing animals, PVSO reduced tumor growth, and suppressed serum and hypothalamic inflammatory cytokines (TNF-α, IL-1β, and IL-6) and NF-κB signaling." (PMID 40993108, 2025).
tumor (continued). "uPA deficiency resulted in increased CD8+ T-cells infiltration and cytotoxicity via increasing GzmB, IFN-γ, and TNF-α secretion, further suppressing tumor growth." (PMID 40959092, 2025). "These cells sustain the tumor’s quiescence by secreting pro-inflammatory cytokines, such as TNFα and IFN-γ." (PMID 40977686, 2025). "This suggests that the observed univariate correlation between TNF-α and CEA was largely mediated by their mutual association with the other tumor markers (particularly CA19-9 and CA72-4)." (PMID 40299527, 2025). "Tumor-transformed hepatocytes exhibit increased anaerobic glycolysis and secrete signaling molecules, including L-6, tumor necrosis factor alpha (TNF-α), and exosomal miRNAs, into the microenvironment." (PMID 40942182, 2025). "TNF-α promotes tumor cell death by killing T cells or other cells, and IL-1β and IL-6 play important roles in immune response and protein synthesis during the acute phase." (PMID 39857446, 2025). "The VS tumor samples showed high variability in their secreted levels of TNF-α (coefficient of variation [CV]: 444.3%, range: 0–1,681 pg/mL)." (PMID 39923035, 2025). "T-lymphocytes have a direct action on cancer cells while B lymphocytes release cytokines like interferon-gamma and tumor necrosis factor-alpha which effectively neutralize tumor cells." (PMID 40740873, 2025). "In KRAS-mutant lung cancer, MAPK and CDK4/6 inhibitors induce senescence and SASP activation, leading to NK cell-mediated tumor cell death through SASP factors such as TNF-α and ICAM-1." (PMID 40781676, 2025). "Interleukin-6 (IL-6) and tumor necrosis factor alpha (TNF-α) induce neutrophilia by promoting the paraneoplastic production of myeloid growth factors by tumor cells." (PMID 40095867, 2025). "To verify the safety of EA in tumor treatment, we used ELISA to detect circulating inflammation cytokines IL-6, TNFα and TGFβ, which significantly contribute to tumor progression." (PMID 40475010, 2025). "A recent study shows that IL-1β–producing TAMs can be elicited by prostaglandin E2 and TNF-α presented in the tumor microenvironment." (PMID 41243973, 2025). "Surprisingly, TNF-α, recognized for its tumoricidal potential, can also promote immune escape and tumor progression in liver cancers by upregulating the IFN-γ-receptor and induction of PD-L1 expression." (PMID 40909948, 2025). "In the KOPN-49 and REH experiments, where CHZ868 demonstrated synergistic effects in the tumor rechallenge test, IFN-γ and TNF secretion was also maintained during the third tumor rechallenge, even in REH cells with wild-type JAK2." (PMID 39891728, 2025). "For example, MDSCs are known to promote tumor growth by secreting certain factors, such as tumor necrosis factor (TNF)-α and vascular endothelial growth factor (VEGF)." (PMID 41403931, 2025). "Correspondingly, in the context of CAC, TNF-α exerts a significant influence within the tumor microenvironment." (PMID 40109347, 2025). "Both IFN-γ and TNF-α play a role in inhibiting cancer growth through various mechanisms, such as direct tumor reduction and prevention of cancer angiogenesis." (PMID 40370457, 2025). "Numerous differentially expressed genes identified from both comparisons are linked to cell proliferation pathways such as PI3/AKT/mTOR and TNF-α, suggesting a tumor-prone or precancerous state in the mammary glands of tumor-bearing mice." (PMID 41387465, 2025). "These bacteria then kill the tumor cells by destroying blood vessels through TNF-α, and also activate immunity signaling in the tumor cell to stimulate macrophage phagocytosis and autophagy in the tumor cell itself." (PMID 40585846, 2025). "This duality arises from their ability to produce inflammatory cytokines such as IFN-γ and TNF-α, contributing to tumor cell lysis, while also potentially promoting immune suppression through IL-17, IL-10, and regulatory interactions within the TME." (PMID 40746558, 2025).
tumor (continued). "Anti-TNFα therapies impair this surveillance, allowing newly nascent tumor cells to evade immune detection and elimination." (PMID 40282506, 2025). "TNF-α is recognized as a key factor in many inflammatory, viral, metabolic, and neoplastic diseases." (PMID 39911325, 2025). "Upon activation from tumor ligands, NK cells rapidly produce abundant IFNγ and TNFα in the presence of IL-12/IL-18 derived from activated tumor-resident macrophages and DCs." (PMID 40410571, 2025). "The engineering of OVs to express cytokines such as IL-2, IL-12, and TNF has shown therapeutic efficacy in mouse tumor models." (PMID 40061139, 2025). "Metastatic tumor cells also secrete IL‐23, which induces TNF‐α production in LSECs, upregulating MMP9 and ICAM1 expression and promoting the formation of endothelial cell gaps." (PMID 40027151, 2025). "RT released HMGB1 from tumor cells that induce high TNF-α and low levels of IL-10 secretion from M1-type macrophages that exert drastic anti-tumor activity." (PMID 40141437, 2025). "In preclinical models of NASH-related hepatocellular carcinoma, anti-PD1 treatment leads to more and larger tumor nodules, which are linked to an increase in CD8+PD1+CXCR6+TOX+TNF+ T cells." (PMID 40236693, 2025). "TNF-α enhances glycolysis and lactate production in tumor cells via the NF-κB signaling pathway, promoting the expression of GLUT1 and hexokinase 2 (HK2), and thereby facilitating tumor progression." (PMID 41216196, 2025). "Tumor-activated neutrophils release proinflammatory factors (IL-6, IL-8, IL-1β, TNF-α), which activate the ERK pathway and epithelial–mesenchymal transition, driving TC cell migration and invasion." (PMID 40136652, 2025). "Through enzyme-linked immunosorbent assay (ELISA), we found Rplp0 knockdown and immunotherapy combination remarkably augmented the IFN-γ and TNF-α levels in serum, which implies combinational treatment potentiated the anti-tumor immunity in mice." (PMID 40777041, 2025). "Here, we demonstrate that inhibition of TAK1 in tumor cells lowers the threshold for TNF-α-induced cytotoxicity." (PMID 41102176, 2025). "Selective inhibitors like takinib, which sensitize tumor cells to TNF-α-induced cell death, represent one such approach." (PMID 40558596, 2025). "Inhibiting TBK1/IKKε correlated with reduced RIPK1 S25 phosphorylation, shifted TNF signaling toward cell death, and sensitized tumor cells to CD8+ T cell attacks." (PMID 41315176, 2025). "M1‐polarized macrophages can phagocytose tumour cells via Fcγ receptor‐dependent recognition of antibody‐opsonized targets and release pro‐inflammatory cytokines such as TNF‐α and IL‐12, which stimulate local innate immunity and enhance antigen presentation." (PMID 40673641, 2025). "TNF-α and IL-1β, key pro-inflammatory cytokines, are known to enhance angiogenesis, tumor invasion, and resistance to apoptosis." (PMID 40143078, 2025). "Given its tumour-promoting actions, TNF-α blockade, either alone or in combination with immune checkpoint blockade (ICB), has demonstrated antitumour promise." (PMID 41451221, 2025). "Oral administration of H. junceus venom in F3II tumor-bearing mice suppressed tumor growth and decreased serum TNF-α levels, indicating systemic immunomodulation." (PMID 41155199, 2025). "Macrophages facilitate tumor growth, invasion, and immunosuppression via pathways involving TNF, Fas ligand, and IL-10." (PMID 40636453, 2025). "The results showed that OSMR deficiency significantly increased the levels of the anti‐tumor immune cytokines IFN‐γ and TNF‐α." (PMID 39815665, 2025). "Lymphocytes, crucial mediators of antitumor immunity, produce cytokines such as INF-γ and TNF-α, facilitating tumor cell apoptosis and influencing overall immune competence." (PMID 40224488, 2025). "In recent years, new ideas for optimizing tumor immunotherapy have emerged, such as combination therapy targeting TNF-α signaling." (PMID 41376630, 2025).